DLK1 (delta like non-canonical Notch ligand 1)
Diseases named in the same sentence as DLK1 in open-access papers (continued):
Sharing a sentence is not in itself a finding about the gene and the disease.
central precocious puberty (14 papers, 2018 to 2025). "DLK1 appears to act upstream of the kisspeptin system, with evidence indicating that loss-of-function mutations in DLK1 can lead to central precocious puberty in humans." (PMID 40275190, 2025). "DLK1 has garnered increasing interest in recent years since paternally inherited genetic variants of DLK1 have been identified in families with nonsyndromic central precocious puberty (CPP) with a metabolic phenotype." (PMID 39468766, 2025). "In particular, loss-of-function mutations in the paternally expressed imprinted genes makorin ring finger 3 (MKRN3) and delta-like 1 homolog (DLK1) have been shown to cause central precocious puberty, suggesting the important role of imprinted genes in regulating puberty timing." (PMID 38909248, 2024). "However, until now only the kisspeptin system KISS1/KISS1R, MKRN3, and DLK1 or Pref-1 identified in sporadic or familial central precocious puberty cases have been confirmed causal variants leading to CPP." (PMID 34748517, 2021). "Recently, loss-of-function mutations in the paternally expressed delta-like homologue-1 gene (DLK1), located at 14q32, have been linked to central precocious puberty (CPP)." (PMID 33808370, 2021). "In fact, Bessa analyzed a small cohort of 10 Brazilian girls affected by familial forms of central precocious puberty, some of them with known mutations in the MKRN3 and DLK1 genes." (PMID 38909248, 2024). "Although mutations in multiple genes such as kisspeptin system, MKRN3, DLK1 have been identified in sporadic and familial cases of central precocious puberty (CPP), many factors involved in pubertal initiation and transition remain poorly understood." (PMID 33381157, 2020). "More direct evidence was provided by the demonstration that central precocious puberty (CPP) due to loss-of-function mutations in the paternally expressed imprinted genes MKRN3 (makorin ring finger 3) and DLK1 (delta-like 1 homolog) is an imprinting disorder." (PMID 30466473, 2018). "Mutations in Delta Like Non-Canonical Notch Ligand 1 (DLK1), a paternally expressed imprinted gene, underlie central precocious puberty (CPP), yet the mechanism remains unclear." (PMID 40924042, 2025). "Mutations in Delta-like homolog 1 (DLK1), the kisspeptin system (KISS1 and KISS1R), and the Makorin RING-finger protein 3 (MKRN3) gene have been identified in sporadic and familial cases of central precocious puberty." (PMID 39010901, 2024). "More recently, several mutations in a second maternally imprinted gene, Delta-like noncanonical Notch ligand (DLK1) have also been associated with central precocious puberty." (PMID 36093089, 2022). "Consistent with this hypothesis, partial deletion of the paternally expressed gene DLK1 was reported in a family with familial central precocious puberty when deletion was inherited from the father although this family shows incomplete penetrance for the trait." (PMID 31014393, 2019). "These included the imprinted gene makorin ring finger protein 3 (MKRN3), paternally inherited mutations that have been identified as causal in pedigrees of central precocious puberty (CPP), and delta like non-canonical Notch ligand 1 (DLK1)." (PMID 31220230, 2019).
glioma (12 papers, 2009 to 2022). A benign or malignant brain and spinal cord tumor that arises from glial cells (astrocytes, oligodendrocytes, ependymal cells). "Delta Like Non-Canonical Notch Ligand 1 (DLK1) is a transmembrane protein previously associated with glioma progression." (PMID 32205867, 2020). "Astrocytes represent a prominent cell type in the brain tumor microenvironment, and recent studies revealed that DLK1 is one of the top upregulated genes in tumor-associated astrocytes of high-grade vs low-grade gliomas." (PMID 33142235, 2020). "Tumor-associated astrocytes in a glioma mouse model expressed DLK1 in perinecrotic and perivascular tumor areas." (PMID 33142235, 2020). "DLK1 gene expression was previously reported to be upregulated in isolated GFAP+ tumor-associated astrocytes of high-grade glioma compared to those of lower-grade tumors, further confirming DLK1 expression in astrocytes in this model system." (PMID 33142235, 2020). "Expression of DLK1 is increased with tumor grade in glioma, and its signaling has been associated with various properties of aggressive tumor cells." (PMID 33142235, 2020). "We previously identified soluble Delta Like Non-Canonical Notch Ligand 1 (DLK1) as a factor that promotes glioma growth and stemness and is secreted in the medium of hypoxic astrocytes." (PMID 33802060, 2021). "In spite of the close structural relation between DLK1 and canonical Notch ligands, mechanisms of DLK1 signaling in glioma appear to be more complex than inhibition of Notch receptor activation." (PMID 32205867, 2020). "Mechanistically, DLK1-mediated effects on glioma cells involved increased and prolonged stabilization of hypoxia-inducible factor 2alpha, and inhibition of hypoxia-inducible factor 2alpha activity abolished effects of DLK1 in hypoxia." (PMID 33142235, 2020). "Taken together, these data demonstrate that soluble DLK1 is able to induce glioma cell proliferation, irrespectively of its origin." (PMID 33142235, 2020). "Together, these data suggest that DLK1 promotes the glioma stem cell character in part via HIF-2a stabilization." (PMID 33142235, 2020). "Glioma cells exposed to recombinant DLK1 displayed increased proliferation, enhanced self-renewal and colony formation abilities, and increased levels of stem cell marker genes." (PMID 33142235, 2020). "Here, we found that Delta Like Non-Canonical Notch Ligand 1 (DLK1) expression was elevated as compared with normal brain in a genetically engineered mouse model of glioma, and that DLK1 expression increased with tumor grade in human glioma samples." (PMID 32205867, 2020). "Forced expression of soluble DLK1 resulted in more aggressive tumor growth and shortened survival in a genetically engineered mouse model of glioma." (PMID 33142235, 2020). "Soluble DLK1 increased proliferation and stem cell characteristics of glioma cells, and promoted tumor growth in a genetically engineered mouse model of glioma." (PMID 33142235, 2020). "Together, our data support DLK1 as a soluble mediator of glioma aggressiveness derived from the tumor microenvironment." (PMID 33142235, 2020). "DLK1 expression was highest in hypoxic and perivascular tumor areas, and we found that hypoxia induced the release and nuclear translocation of an intracellular fragment of DLK1 in murine glioma as well as in human glioma cultures." (PMID 32205867, 2020). "Expression of a cleavable form of DLK1 amplified several hypoxia-induced traits of glioma cells such as colony formation, stem cell marker gene expression, a PI3K-pathway-mediated metabolic shift, and enhanced invasiveness." (PMID 32205867, 2020). "Here, we sought to investigate the role of soluble DLK1 in the high-grade glioma tumor microenvironment." (PMID 33142235, 2020).
glioma (continued). "As with astrocyte-derived DLK1 in regulation of normal neural stem cells, the exact mechanism(s) by which soluble DLK1 signals to glioma cells remains to be investigated." (PMID 33142235, 2020). "We describe one such example here: soluble DLK1 secreted from astrocytes appears to be involved in stem cell maintenance both of normal neural stem cells and glioma cells, as shown here." (PMID 33142235, 2020). "To test the effects of soluble DLK1 on glioma growth in vivo, we generated a mouse model for the overexpression of soluble DLK1 together with PDGFB using the RCAS/tv-a system." (PMID 33142235, 2020). "In a previous study, we described release of and signaling from the intracellular domain of DLK1 in glioma cells." (PMID 33142235, 2020). "Taken together, our data support a role for soluble DLK1 as a tumor-promoting stem cell niche factor in glioma." (PMID 33142235, 2020). "The protein has been suggested as a Notch inhibitor, which is supported by the finding that Hes-1 was downregulated in glioma cell lines stably expressing Dlk1 or treated with Dlk1-conditioned medium." (PMID 25601901, 2014). "Dlk1 expression is increased in gliomas and over-expression in transfected cells promotes cell proliferation by inducing the expression of cyclin D1, CDK2, and E2F4." (PMID 19331679, 2009). "Similarly, while stimulation of glioma cells with soluble DLK1 boosted the increase in the expression of the stem cell marker genes NANOG, OCT4, and SOX2 in hypoxic cells, addition of PT2385 blocked this specific DLK1 effect in all cell lines tested." (PMID 33142235, 2020). "Together, these data support that astrocytes may secrete DLK1 into the tumor microenvironment in glioma." (PMID 33142235, 2020). "As HIF-2a is a known driver of stem cell characteristics in glioma and other tumor forms [31,23,], we next tested whether effects of DLK1 on glioma cell behavior were mediated by HIF-2a." (PMID 33142235, 2020). "Importantly, however, HIF-2a inhibition did not significantly affect DLK1-mediated stem cell marker expression under normoxic conditions, suggesting that there are other mediators downstream of DLK1 that can contribute to DLK1 signaling in glioma." (PMID 33142235, 2020). "Analysis of DLK1 expression in the Cancer Genome Atlas (TCGA), in the Chinese Glioma Genome Atlas (CGGA) datasets and evaluation of DLK1 stainings in low- vs high-grade murine tumors revealed higher DLK1 expression in high-grade gliomas, that typically have hypoxic areas." (PMID 32205867, 2020). "We employed a panel of glioma cultures to characterize DLK1 under normoxic and hypoxic conditions." (PMID 32205867, 2020). "Moreover, PT2385 decreased the colony formation ability of glioma cells exposed to soluble DLK1 in hypoxia." (PMID 33142235, 2020). "Moreover, analysis of PDGFB/shp53-induced murine gliomas revealed that both DLK1 and HIF-2a were strongly expressed and showed a significant co-localization only in the perivascular and perinecrotic niches." (PMID 33142235, 2020). "•Soluble DLK1 promotes stemness in glioma, in part by increasing HIF-2alpha stabilization." (PMID 33142235, 2020). "Since many of the proteins with significant variations detected in the proteome profiler array are involved in extracellular matrix remodeling and degradation, we investigated whether expression of the various DLK1 forms could influence the invasive behavior of glioma cells." (PMID 32205867, 2020). "Because DLK1 secretion was increased by astrocytes under hypoxic conditions, and because of known previous links between DLK1 expression and function to hypoxia, we asked whether soluble DLK1 could influence the hypoxic response of glioma cells." (PMID 33142235, 2020). "We next examined what effect soluble DLK1 may have on glioma cells." (PMID 33142235, 2020).
glioma (continued). "Furthermore, it is somewhat counterintuitive that soluble DLK1 appears to simultaneously promote glioma cell proliferation and stem cell characteristics, as it is widely assumed that stem-like cells display lower proliferation rates than more differentiated, non−stem-like cells." (PMID 33142235, 2020). "Tumor-associated astrocytes represent a major component of the glioma tumor microenvironment, and astrocytes have an active role in maintenance of normal neural stem cells in the stem cell niche, in part via secretion of soluble delta-like noncanonical Notch ligand 1 (DLK1)." (PMID 33142235, 2020). "Among the human glioma cell lines and genetically engineered glioma mouse model tested in this study, all but one cell line (U3065MG) responded to soluble DLK1." (PMID 33142235, 2020). "Here, we used mouse models of glioma and human GBM cultures to characterize the expression, regulation, and function of DLK1 in GBM." (PMID 32205867, 2020). "The DLK1 expression is observed to elevate in gliomas, and overexpression of DKL1 in glioma cell line simulated cells proliferation." (PMID 29348851, 2017). "As more in-depth research developed, the contribution of Notch signaling in glioma progression is extended to non-canonical Notch ligand 1 (DLK1)." (PMID 33381038, 2020). "In the model systems investigated here, DLK1 overexpression was not sufficient to drive a lower survival rate of glioma-bearing mice, but tumors generated to express DLK1 did show a more invasive growth pattern." (PMID 32205867, 2020). "Finally, forced expression of DLK1 resulted in more invasive tumor growth in a PDGFB-induced glioma mouse model without affecting overall survival." (PMID 32205867, 2020). "PDGFB-induced glioma primary cultures (PIGPC) and GBM cultures maintained under serum-free conditions (U3046MG, U3035MG, U3082MG, U3084MG, and U3065MG) showed a band pattern similar to murine glioma, while serum-cultured cell lines T98G and U251MG showed a single DLK1 band." (PMID 32205867, 2020). "The mechanisms involved in regulating DLK1 cleavage by ADAM17 appear to be complex, as we did not detect the intracellular fragment in four tested glioma cell lines in hypoxia." (PMID 32205867, 2020).
Temple syndrome (12 papers, 2019 to 2025). "Loss of paternally inherited DLK1 is reported to frequently cause precocious puberty in females with Temple syndrome." (PMID 32878913, 2020). "The syntenic area on human chromosome 14 is the critical region for Temple Syndrome, and loss of DLK1 expression is thought to cause phenotypes associated with this disorder; pre-and postnatal growth restriction with increased truncal obesity and precocious puberty." (PMID 37589451, 2023). "Temple Syndrome and DLK1 mutations in humans are associated with precocious menarche." (PMID 37589451, 2023). "We describe a girl with clinical presentation suggestive of Temple syndrome resulting from a small paternal 14q32 deletion that led to DLK1 whole-gene deletion, as well as hypermethylation of the maternally methylated DLK1-DMR." (PMID 38715103, 2024). "According to a different study, the Dlk1/Meg3 region is hypomethylated in children with temple syndrome, a condition marked by pre- and postnatal growth retardation, feeding difficulties, and motor development delay." (PMID 39543691, 2024). "Since ZNF445 binds to the MEG3/DLK1:IG-DMR and other iDMRs affected in this patient, the development of Temple syndrome and MLID would primarily be explained by the ZNF445 variant." (PMID 34039421, 2021). "Similar to MKRN3, DLK1 gene also locates in a maternal imprinting region located in 14q32, which is originally reported as a critical region of Temple syndrome." (PMID 31687022, 2019). "Both genes are located at critical regions of imprinting disorders that may be associated with CPP (MKRN3 at chromosome 15q11-q13 of Prader-Willi syndrome and DLK1 at chromosome 14q32.2 of Temple syndrome)." (PMID 37385287, 2023). "In mice, ZFP57 plays the predominant role in the maintenance of imprinting, whereas, in its absence, ZFP445 is required to preserve methylation in a subset of imprinting control regions such as those present in the MEG3/DLK1:IG-DMR, that involved in Temples’ syndrome." (PMID 38909248, 2024). "Therefore, it is clear that combined and differential involvement of DLK1 and RTL1 should be considered when investigating the symptoms of Temple syndrome." (PMID 32878913, 2020). "DLK1 hypomethylation may be considered in patients with sporadic CPP, as in Temple syndrome where CPP has been ascribed to different methylation and expression of the maternal and paternal DLK1-DIO3 gene cluster, which is controlled by the imprinting control region IG-DMR." (PMID 39704935, 2025). "Particularly, we predict that in patients with Temple Syndrome (TS14), and in some patients with the clinically overlapping Silver-Russell Syndrome (SRS), their aberrant, biallelic MEG3 expression would lead to strongly reduced DLK1 in tissues in which this non-canonical Notch ligand is imprinted." (PMID 38613389, 2024).
atherosclerosis (11 papers, 2015 to 2025). A disease characterized by the build-up of fatty material and calcium deposition in the arterial wall resulting in partial or complete occlusion of the arterial lumen. "MiR-126-5p promotes angiogenesis and protects atherosclerosis by suppressing the Notch1 inhibitor Delta Like Non-Canonical Notch Ligand 1 (DLK1)." (PMID 36765409, 2023). "Other studies suggest that miR-126-5p promotes endothelial cell growth and restricts atherosclerosis by inhibiting Dlk1." (PMID 35582235, 2022). "Endothelial miR-126-5p promotes endothelial proliferation and limits atherosclerosis by suppressing expression of delta-like 1 homolog (Dlk1)." (PMID 34150863, 2021). "MiR126 has also been shown to prevent atherosclerosis formation by promoting endothelial cell proliferation and turnover, through the suppression of the Notch1 inhibitor delta-like 1 homolog (Dlk1)." (PMID 26331273, 2015). "MiR-126 promotes endothelial proliferation and limits atherosclerosis by suppressing Dlk1." (PMID 33671744, 2021).
type 2 diabetes mellitus (11 papers, 2010 to 2026). A type of diabetes mellitus that is characterized by insulin resistance or desensitization and increased blood glucose levels. "Along with TRIM28 and NOTCH3, one of our most interesting discoveries in the ART placentas concerned the prominent downregulation of imprinted DLK1 as well as the pathways of insulin secretion and maturity onset diabetes of the young, which came forth in the DNAm analyses." (PMID 39702541, 2024). "DLK1 is a β-cell gene heterogeneously expressed between cells and islets of non-diabetic (ND) and type 2 diabetes (T2D) humans." (PMID 40982369, 2025). "We screen 99 phenotypes for parent-of-origin effects and replicate the discoveries of 6 GWAS studies, confirming signals on body mass index, type 2 diabetes, standing height and multiple blood biomarkers, including the known maternal effect at the MEG3/DLK1 locus on platelet phenotypes." (PMID 36335127, 2022). "In addition, reduced expression of Dlk1-Dio3 miRNAs, specifically in islet β cells of human patients with type 2 diabetes mellitus (T2DM), has been associated with DNA hypermethylation at MEG3-DMR in the β cells from T2DM donors." (PMID 34062726, 2021). "Interestingly, in patients with type 2 diabetes, serum HER-2 concentrations were positively associated with serum soluble tumor necrosis factor-α (TNF-α) receptor 1 [r = 0.65, p = 0.001, n = 21] and serum DLK-1 (r = 0.81, p = 0.007, n = 9) (data not shown)." (PMID 20184722, 2010).